MYC (MYC proto-oncogene, bHLH transcription factor)
Diseases named in the same sentence as MYC in open-access papers (continued):
Sharing a sentence is not in itself a finding about the gene and the disease.
cancer (continued). "When determining the impact of the miRNA signature on DLBCL biology, it was discovered that these miRNAs had the most prominent impact on genes, MYC and JUN, with global impact on cancer related functions starting at age several months before actual DLBCL formation." (PMID 28107482, 2017). "The metabolic rewiring of cancer cells relies on a hierarchical oncogenic cascade involved in Akt/mammalian target of rapamycin (mTOR), mitogen-activated protein kinase (MAPK) signaling, and, essentially, a MYC dependent metabolic transcriptome." (PMID 28245597, 2017). "Several new associations with ETS negative cancers were found, including deletions at 1q42.2-q42.3 & 4q22.3, and amplifications at 3q22.1-q21.3, 7p11.2 (EGFR), & 8q (MYC)." (PMID 28945760, 2017). "These interactions exemplify the intricate relationship between MYC and CDKs, and demonstrate a potential benefit from disrupting these feedback loops therapeutically, since CDK/cyclin complexes are also found frequently deregulated in cancers." (PMID 28333115, 2017). "It is more interesting that MYC and BCL2 may act synergistically to promote the generation of cancer cells." (PMID 28615526, 2017). "A recent study showed that aurora A kinase and the targeting protein for Xklp2 (TPX2) are novel co-regulators of the MYC pathway, suggesting that targeting of the aurora A kinase/TPX2 axis could be a therapeutic approach for MYC-driven cancers." (PMID 28036279, 2017). "SQLE is often co-amplified with the cancer driver MYC but SQLE expression is prognostic independent of MYC status." (PMID 27358048, 2016). "Moreover, inhibitors of BET binding can disrupt the growth of cancer cells and this phenomenon has been attributed to the acute sensitivity to BET disruption of super-enhancers at oncogenes such as MYC and BCL2." (PMID 27097319, 2016). "Previous work established that in cancer cell lines, excess PI3K pathway signaling modulates the AKT-regulated targets GSK3β and mTOR, extending the half-life of MYC and outlining a potential pharmacologic approach for targeting MYC stability." (PMID 27438153, 2016). "8q24.12-24.13 location myelocytomatosis oncogene (MYC), MYC is a group of cancer genes, which are not expressed in normal cells, and expressed in some cancer cells." (PMID 27634905, 2016). "In contrast, our analysis of E1A 1-80 expressed in cancer cells suggests that targeting of p300 by E1A 1-80 is correlated with inhibition of MYC promoter H3K18 acetylation and may contribute to MYC repression." (PMID 27382434, 2016). "Furthermore, analysis of TCGA datasets using the cBioPortal for Cancer Genomics indicated a correlation between MYC amplification and/or increased mRNA expression and increased POLRMT mRNA expression in cancer patient samples." (PMID 27590350, 2016). "ST expressing cells were also significantly enriched for the Cancer Hallmarks including epithelial to mesenchymal transition (EMT), TNFA signaling via NF-κB, hypoxia, mTORC1, oxidative phosphorylation, glycolysis, MYC, and cell cycle including E2F targets, G2/M checkpoint and mitotic spindle." (PMID 27880818, 2016). "We begin by exploring the partnership between MYC and HIF-1 in reprogramming cancer metabolism." (PMID 27447861, 2016).
cancer (continued). "Moreover, MYC upregulates the glutamine transporters SLC5A1 and SLC7A1, which contribute to glutamine uptake in cancer cells." (PMID 27455839, 2016). "In fact, recent studies reported that CB suppresses cell proliferation and induces cell cycle arrest and apoptosis through downregulation of p-ERK, c-MYC, p-GSK-3β, NK-κB/p65, and p38 MAPK, but upregulation of intracellular free calcium ([Ca2+]i) and Cyclin A in cancer cells." (PMID 26959116, 2016). "From these samples, we identify established driver aberrations in a cancer-related gene in nearly all cases (97.7%), including driver gene fusions (TMPRSS2:ERG), driver focal deletions (PTEN, RYBP and SHQ1) and driver amplifications (AR and MYC)." (PMID 27328849, 2016). "This dependence is driven by the activation of MYC and HIF1-α and consequently, targeting pathways regulating glucose/glutamine metabolism may be of relevance for cancer treatment." (PMID 27455839, 2016). "When the mTOR-mediated phosphorylation of 4EBP1 was blocked in MYC driven cancers by MLN0128, which specifically blocks the mTOR active site by inhibiting 4EBP1 phosphorylation, it specifically induced significant apoptosis in the MYC driven pre-tumor B cells, while sparing the wild type B cells." (PMID 28025559, 2016). "Notably, an increased aldehyde dehydrogenase activity, along with an increased expression of c-MYC and activation of the WNT/β-catenin, is a feature of cancer stem cells." (PMID 27655693, 2016). "It is worth mentioning that, to date, no effective MYC inhibitors have been developed despite the fact that MYC overexpression is frequently found in human cancers." (PMID 28040803, 2016). "c-MYC, ABCG2, NESTIN and OCT4 have important role in cancer progression." (PMID 27054115, 2016). "The HATs KAT2A, 2B, and 5 acetylate the oncogene c-MYC leading to increased stability of the c-MYC protein, which may lead to cancer progression." (PMID 27231488, 2016). "Of interest, several genes, apart from SQLE and MYC, located in the q arm of chromosome 8 may have an even tighter CN-GE correlation than SQLE, and be endowed with essential biological properties for cancer proliferation and survival." (PMID 26777065, 2016). "Overall, MYC overexpression and PVT1 up-regulation have been reported for several human cancers." (PMID 27366943, 2016). "Undoubtedly, some RT-qPCR results did not consist with the microarray analysis, such as c-MYC, which is involved in cell proliferation and results in the formation of cancer." (PMID 27725724, 2016). "MYC Associated Factor X (MAX) plays a key role in the MYC-MAX-MAD gene regulatory network; however, its direct involvement in cancer has not yet been reported." (PMID 27294413, 2016). "The development of novel c-MYC inhibitors that can act by targeting the c-MYC DNA G-quadruplex at the level of transcription would provide potential insight into structure-based design of small molecules and lead to a promising arena for cancer therapy." (PMID 26286633, 2015).
cancer (continued). "To study, whether PTEN deletion has an additional prognostic value in cancers harboring co-amplification of HER2, MYC, or CCND1, we stratified cancers for survival analysis according to the status of PTEN and HER2, PTEN and MYC, as well as PTEN and CCND1." (PMID 26672755, 2015). "Although there have been several reports on c-MYC status in human cancers, there are no established criteria for GCN gain." (PMID 26426996, 2015). "Furthermore c-MYC and PIM1 have also been shown to cooperate in prostate tumourigenesis, while the inhibition of PIM kinases in c-MYC-expressing cancers decreases proliferation, survival and tumourigenicity." (PMID 26643319, 2015). "In addition, the rest of TFs such as PPARG, PPARA, SMAD3, MYC, and STAT1 have been proved to be related to cancer progression." (PMID 26425543, 2015). "In cancer samples, CaMKIIγ was positively correlated with OCT4 and MYC." (PMID 25965829, 2015). "Patients with copy number gains of MYC had poor overall survival compared to those without, but the difference was not statistically significant in diffuse type and intestinal type cancers." (PMID 26360582, 2015). "In addition, the rest of 11 TFs such as SAMD4, MYC, PPARG, and PPARA have also been proved to play key roles in various cancer progressions." (PMID 26425543, 2015). "The significant down-regulation of cyclin B, cyclin D1, E2F1, survivin, and c-MYC in human RCC cells mediated by ART may be sufficient to arrest cell cycle progression and to suppress cancer stemness." (PMID 26426994, 2015). "NF-κB pathway plays an important role in regulating cancer cells proliferation, anti-apoptosis, invasion and metastasis and angiogenesis, through modulating series of functional genes expression and activity, including IL1A, CCND1, MYC, Bcl-2, MMP9 and VEGF." (PMID 26429874, 2015). "Oct4 and CIP2A co-expression with MYC in TCs was also very obvious and only two cancer samples were MYC negative." (PMID 25474139, 2015). "It is currently unknown whether SIRT1 regulates the metabolic effects of MYC in cancer; however, based on these findings, it is likely that SIRT1 can induce expression of MYC target genes important in mediating metabolic reprogramming." (PMID 25085992, 2014). "Specifically, the authors hypothesized that blocking HUWE1expression or function would stabilize MIZ1 and lead to binding of MIZ1 to MYC:MAX complexes at keytarget genes, to switch transcription into an off state and disable cancer cell growth." (PMID 25368331, 2014). "Our hypothesis is that in cancer cells, MYC overexpression induces DSBs and PRKDC plays a pivotal function in repairing this DNA damage, leading to cancer cell survival." (PMID 25495526, 2014). "Consistent with this notion, we discovered that JQ1 inhibits MYC expression in all BL-derived cells tested but does not inhibit MYC expression in some other cancer cell lines, as observed earlier." (PMID 24466310, 2014). "For example, various transcriptional inhibitors induce the downregulation of anti-apoptotic proteins, such as Mcl-1, XIAP and survivin, or oncogenes, such as MYC, without disrupting the transcription of normal genes in cancer cell lines." (PMID 24576043, 2014). "It appears from the results from different laboratories who studied the tumorigenic involvement of CIP2A, PP2A and c-MYC in different organ-type cancers, that CIP2A forms an important component of the “oncogenic nexus” in concert with PP2A and c-MYC in achieving the tumorigenic effect in cells." (PMID 25015035, 2014). "Today deregulated MYC expression is recognized as a crucial driving force in many, if not most human cancers." (PMID 25326649, 2014).
cancer (continued). "A key function of MYC in cancers is regulating the absorption and metabolism of the non-essential amino acid glutamine." (PMID 25085992, 2014). "We concluded that both compounds inhibit MYC-dependent transactivation incolon cancer cells, but not in normal intestinal epithelial cells and embryonic stem cells.In vitro assays revealed that both compounds are unstable in the presence ofmicrosomes." (PMID 25253726, 2014). "It is therefore not surprising that deregulation of MYC proteins contributes to the development of a wide variety of human cancers." (PMID 24515800, 2014). "Both MYC and HIF-1α are direct targets of the RAS-BRAF-MEK-ERK pathway, suggesting an overall role of this pathway in the formation of various metabolic traits of cancer, including the “Warburg effect”." (PMID 23603840, 2013). "These cancer pathways comprise many genes downstream of known oncogenes, like RAS and MYC." (PMID 23379751, 2013). "If so, T-cells of HLA-A2-positive cancer patients may be equipped with HLA-A2/c-MYC-specific TCR genes by retroviral gene transfer and such T-cells administered to HLA-A2-positive cancer patients." (PMID 24130880, 2013). "Most importantly, at Cancer Research UK in Cambridge, David Tuveson's laboratory has recently shown that Nrf2 synthesis is somehow upregulated by the cell growth and division-promoting RAS, RAF and MYC oncogenes." (PMID 23303309, 2013). "In agreement with the present findings, metabolic control by V600EBRAF could be envisaged on the basis of its signaling through the MEK and ERK kinases and activation of MYC or HIF-1α, both of which are major determinants of cancer metabolism." (PMID 23603840, 2013). "Considering the closest flanking genes of intergenic SNPs, the following are noteworthy and could contribute to the carcinogenic process, as has been reported for other cancer types: PRDM1, ATG5, MYC, EID, RLN1, CD274." (PMID 23626673, 2013). "MYC-proteins (c-MYC, MYCN and L-MYC) represent a family of transcription factors which are of particular therapeutic interest because of their strong over-expression in many human cancers." (PMID 22860051, 2012). "This site binds several different transcription factors and has been shown to interact with the MYC promoter in various cancer cell lines including MCF7 cells (the interaction has not been investigated in T47D or MDA-MB-231 cells to our knowledge)." (PMID 23145106, 2012). "c-MYC (henceforth MYC) is an immediate-early serum response gene essential for embryonic development, cellular proliferation and survival, and a cellular proto-oncogene that is frequently up-regulated in cancer." (PMID 22373487, 2012). "Such a set of hubs contained important transcription factors such as MYC and E2F1 and oncogenes such as JUN and RELA and was enriched with genes that appeared in cancer pathways (p<2.2×10−8), the cell cycle (p<3.5×10−6) and several important signaling pathways from DAVID." (PMID 21390271, 2011). "We show in this study that the cytotoxic effects of only a subset of the drugs in our screen were potentiated by MYC overexpression, indicating that overexpression of MYC in cancer cells does not lead to a general sensitization to cytotoxic drugs." (PMID 22132187, 2011). "Identification of pathways that MYC overexpressing cancer cells, but not normal cells, depend upon for their survival is an attractive strategy for understanding the best way of treating MYC-deregulated cancers." (PMID 22132187, 2011). "We found that loss of Rb did not change the number of mice that do not develop HCC within one year, suggesting that Rb deletion does not affect cancer initiation and confirming that tumorigenesis is driven by activation of MYC in this mouse model." (PMID 21573126, 2011).
cancer (continued). "Since it remains unclear to what extent the inflammatory cells in human samples play an active versus bystander role in cancer progression or suppression, the MPAKT/Hi-MYC model may help address this question." (PMID 21394210, 2011). "MYC and RAS are two prototypic oncogenes involvedin development of numerous cancers." (PMID 20445224, 2010). "Recently, MYC protein recruited the PRC2/EZH2/DNMT3B complex to bind to the RASSF1A promoter, which led to RASSF1A gene silencing by promoter CpGs hypermethylation and condensed chromatin in cancer cell." (PMID 20877461, 2010). "Pathways such as MYC and SRC represent one opportunity but the concept can go well beyond to include other, less defined, cancer relevant phenotypes that can be represented as expression signatures including poor prognosis, metastasis, or general resistance to therapies." (PMID 19714244, 2009). "In addition, the oncogene MYC also plays a crucial role in hypoxic response, and cooperates with HIF-1α to alter cellular metabolism and promote cancer progression." (PMID 19948069, 2009). "Our results, highlighting differences in E-box selection between MYCN and c-MYC would indicate that these transcription factors should not be completely functionally redundant in cancer." (PMID 19997598, 2009). "Aberrant hypomethylation has been hypothesized to contribute to cancer progression by activating oncogenes such as h-RAS, r-RAS, c-MYC, and c-FOS, by retrotransposon activation or by increasing chromosome instability as in ICF syndrome." (PMID 18698372, 2008). "For example, K604-Gln-intact cancers could be sensitized to HU and ALS treatments through the Gln-K604 inhibitor glutaminol, whereas Gln-K604-null cancers could be sensitized by silencing c-MYC and MCL-1." (PMID 40338031, 2025). "SE-driven genes, such as MYC, are particularly upregulated in cancer and are challenging to target directly, but this difficulty might be overcome by targeting CDK7.347–349 Studies in multiple types of cancer support this hypothesis." (PMID 39800748, 2025). "As EZH2 and MYC were dysregulated in a range of human tumors, we sought to determine whether squamocin can effectively degrade both EZH2 and MYC in other types of cancer." (PMID 39823459, 2025). "Notably, the control mouse livers with Prtm5 knockout appeared to be normal, indicating that Prtm5 is essential for the MYC-transformed cancer cells but not for the non-transformed liver cells." (PMID 38853928, 2025). "Direct MYC inhibitors, such as Omomyc-derived agents or PROTAC-based degraders, while promising, may encounter limitations as monotherapies due to adaptive resistance mechanisms inherent in cancer biology." (PMID 40365020, 2025). "However, based on the small degree of colocalization between MYC and BAF155, this analysis suggests that retained SWI/SNF subunits may not profoundly contribute to MYC-dependent gene regulation in this cancer context." (PMID 40647552, 2025). "Although MYC was predicted as a cancer reversion target, its single inhibition does not significantly alter the size or width of the cancer attractor and, consequently, does not substantially reduce the cancer score (middle)." (PMID 39840939, 2025). "Third, although MYC and, putatively, E2F and G2M emerge as sufficient drivers of cancer splicing programs, tumors lacking activation of these regulators may employ alternative pathways to modulate initiator splicing factors." (PMID 41101775, 2025). "Furthermore, even if PD-L1 is expressed in cancer cells, it is not responsive to PD-L1 due to the MYC interference of IFN-γ." (PMID 40002814, 2025).